CCL2 (C-C motif chemokine ligand 2)
Diseases named in the same sentence as CCL2 in open-access papers (continued):
Sharing a sentence is not in itself a finding about the gene and the disease.
tumor (continued). "Overall, we identified a peripheral Neuro-Endocrine-Immune pathway SNS/β-ARs/CCL2 in the eustress model to relieve tumor immunosuppression and to overcome PD-1 immunotherapy resistance." (PMID 34593796, 2021). "Tumor cells can secrete colony stimulating factor-1, chemokine (C-C motif) ligand 2 (CCL2), chemokine (C-C motif) receptor 5 (CCR5), chemokine (C-X-C motif) ligand 1 (CXCL1), and so on, to recruit immunosuppressive myeloid cells toward the TME." (PMID 34948368, 2021). "TAMs recruited by CCL2 facilitate early steps of metastases by promoting tumor cell migration and intravasation." (PMID 34824220, 2021). "Bone marrow-derived macrophages are recruited by tumor chemokines such as CCL2 and CSF-1 or their receptors and promote metastasis to bones." (PMID 34204474, 2021). "Several chemokines such as macrophage colony-stimulating factor-1 (MCSF/CSF1) and monocyte chemotactic protein-1 (MCP1/CCL2) are known to contribute to the recruitment of TAMs to the tumor." (PMID 33544755, 2021). "TAMs also secrete anti-inflammatory/immunosuppressive cytokines (e.g., TGFβ, PGE2) and chemokines (e.g., CCL7, CCL2), which promote T-cell exhaustion and establishes a self-propagating tumor-permissive microenvironment." (PMID 34201127, 2021). "CCL2-neutralizing antibodies or v-raf murine viral oncogene homolog B1 inhibitors targeted CCL2 and resulted in marked inhibition of tumor growth in mouse models by suppressing CCL2 gene expression." (PMID 34445235, 2021). "The number of CCL2+ and CCL17+ TANs was found to be associated with tumor size, microvascular invasion, level of tumor differentiation, and staging." (PMID 34200529, 2021). "Most tumor-associated macrophages (TAMs) are derived from monocytes which are constantly recruited into malignant tumors by chemotactic signals generated by the tumor, such as the CCL2 chemokine axis." (PMID 37849947, 2021). "In in vivo models of metastatic prostate cancer, treatment with neutralizing anti-CCL2 antibodies either reduced systemic tumor burden including bone lesions or completely inhibit bone metastases." (PMID 34803925, 2021). "Interaction between CCR2 on monocytes with its ligand (CCL2) induces migration of monocytes from the circulation to the tumor tissue and promotes tumor proliferation." (PMID 34445615, 2021). "Firstly, Snail1 recruits CD4+FOXP3+Treg cells into the tumor microenvironment through C-C motif chemokine ligand 2 (CCL2)." (PMID 34917071, 2021). "CCL2 knockdown leads to a striking reduction in macrophage densities, tumor proliferation, skin erythema, and metastasis." (PMID 34824220, 2021). "Strategies to target CCL2/CCR2 axis as cancer therapy in the view of three types of CCR2-expessing cells in tumor microenvironment are discussed." (PMID 34804061, 2021). "Inhibition of CCL2 blocked macrophage recruitment and angiogenesis, resulting in decreased tumor and blood volumes in an orthotopic human GBM model (U-87 MG cell line) expressing CCL2." (PMID 35047971, 2021). "Although the CCL2–CCR2 axis is primarily considered to be a chemokine pathway involved in myeloid cell-participated immune regulation, CCR2-expressing tumor cells can also directly interact with CCL2 for itself activation." (PMID 34386431, 2021). "It was shown, that circulating monocytes or tissue residing macrophages are recruited and stimulated by different tumor-derived signals, such as chemo-attractants, e.g. CCL2 or cytokines, e.g. IL-4, IL-10 and IL-13." (PMID 34579743, 2021). "The accumulation of MSCs within the tumor stroma is also supported by increasing cytokine concentrations of fibroblast growth factor-2, monocyte chemotactic protein-1 (=CCL2), CCL5, and stromal cell-derived factor 1 (=CXCL12)." (PMID 34680359, 2021). "In MM, the mechanism explaining the increased number of tumour-associated macrophages (TAM) in unclear; however, the roles of CCL2 and CCL3 in the process have been confirmed." (PMID 33808304, 2021).
tumor (continued). "In liver metastases, monocytes and TAMs or MAMs were recruited in liver by tumor cells via CCL2 secretion." (PMID 34067719, 2021). "Specifically, PTEN loss induced upregulation of CCL2 and VEGF expression and inhibited tumor cell autophagy." (PMID 33981303, 2021). "As pancreatic tumorigenesis proceeds, C-C motif chemokine ligand 2 (CCL2) is released by the tumor cells, leading to substantial attraction of circulating monocytes to the TME." (PMID 34204306, 2021). "The monocyte chemotactic protein-1, or CCL2, regulates polarization of M1 and M2 phenotypes and recruits TAMs to the tumor microenvironment." (PMID 34108518, 2021). "CCL2+ TAMs are related to the immune response and exhibit a high capacity for apoptosis, while CD44+ TAMs are associated with tumor angiogenesis." (PMID 34824203, 2021). "In experimental models, HSPCs promote tumor cell proliferation, expression of the immune checkpoint PD-L1 and secretion of tumor promoting cytokines such as IL-6, IL-8 and CCL2, indicating concomitant support of both malignancy and immunosuppression." (PMID 34162860, 2021). "E.g., CCL2 was inhibited to reduce TAM recruitment to the tumor, and CD47 has been targeted to reduce its inhibitory effect on TAM phagocytosis." (PMID 34503065, 2021). "Enhanced NF-κB activity leads to tumor rejection and suppresses tumor growth via upregulating the expression of several T cell chemokines, including CCL2, CCL5, and recruiting cytotoxic CD8 T cells." (PMID 34277453, 2021). "Objective response rate (complete or partial response) was significantly correlated to tumor microenvironment-related SNPs concerning CCL2, NOS3, IL1RN, IL12B, CXCR3, and IL6R genes." (PMID 32733486, 2020). "CCR2 expression was detected on monocytic myeloid cells including CD14 monocytes and its myeloid precursors, whereas its specific ligand CCL2 (MCP1) is produced by tumor and stromal cells." (PMID 31811337, 2020). "The overexpression of CCL2 and resultant promotion of tumor growth have also been observed in breast, ovarian, esophageal, gastric, renal cell, lung, colon, and papillary thyroid cancers." (PMID 32471499, 2020). "Together, these studies suggest that matrix stiffness increases CCL2 levels, which in turn recruits specific macrophage populations that interact with collagen fibers and facilitate tumor cell dissemination." (PMID 32509583, 2020). "Multivariate Cox’s regression analysis (adjusted for tumor stage, lymph node stage, and molecular subtype) showed that CCL2 staining was an independent predictor of DSS (RR = 1.77; p = 0.031) but not for OS or RFS." (PMID 32429318, 2020). "CCL2 also promotes tumor angiogenesis at metastatic sites, suggesting that the targeting of this chemokine would be a promising strategy." (PMID 33022971, 2020). "Subsequently, CCL2 activated by LNMAT1 recruits macrophages into the tumor mass and promotes the lymphatic metastasis via VEGF-C excretion." (PMID 32083005, 2020). "CXCL1, CXCL2, and CXCL5 have been shown to recruit MDSCs to the pre-metastatic niche through the interaction with CXCR2; once in the pre-metastatic site, MDSCs favor tumor cell recruitment and seeding by secreting TNFα, TGFβ, IL-6, CCL2 and CXCL2." (PMID 32823961, 2020). "The decrease in the levels of Fosl1, Ccl2, and Ccl3 is expected to reduce the recruitment of cells that allow tumor cells to evade the immune surveillance, e.g., TAMs, regulatory T cells (Tregs), and myeloid-derived suppressor cells (MDSCs)." (PMID 33330473, 2020). "Although the pro-inflammatory chemokine Ccl2 was highly activated in the LLC-derived tumor, we found that the Il1rn level was increased in LLC-derived tumor tissue (~four-fold) and its corresponding TILs (~50-fold) when they were compared to LLC cell line." (PMID 32244522, 2020). "The mRNA expression of different pro-tumor factors such as interleukin-1β (IL-1β), CC-chemokine ligand-2-4 (CCL2, CCL3, CCL4), Interleukin-23 (IL-23) and inducible nitric oxide synthase (iNOS), was analyzed." (PMID 33049964, 2020).
tumor (continued). "Targeting the CCR2/CCL2 pathway showed effectiveness in other tumor models as it suppresses tumor progression." (PMID 32668709, 2020). "The data indicated that imperatorin suppressed metastasis of ESCC cells, whereas the injection of CCL2 via tail vein, which mimicked a “rescue” paracrine effects of fibroblasts, significantly attenuated the inhibitory effect of imperatorin on tumor metastasis." (PMID 32832354, 2020). "After local ablative radiation, the STING/IFNγ pathway enhances tumor radioresistance by inducing the expression of CCL2, CCL7, and CCL12, which attract CCR2+ MDSCs into the TME." (PMID 32942545, 2020). "Monocytic MDSCs and inflammatory monocytes migrate to the tumor area via the CCL2/CCR2 and CSF pathways and are differentiated into TAMs through various factors secreted by tumor cells." (PMID 32726950, 2020). "CCL2 produced both in the target organ and in tumor can promote M-MDSC (defined as CD11b+CD115+Ly6Chi cells) recruitment to the metastatic niche." (PMID 32133298, 2020). "Tumor cell products (such as IL-10, IL-4, and CCL2) affect the M1/M2 transformation of TAMs, and TAMs, in turn, regulate the biological behavior of tumor cells by secreting small molecular substances." (PMID 32653013, 2020). "Lymph node metastasis associated transcript 1 (LNMAT1), also a new lncRNA, is involved in the regulation of C-C motif chemokine ligand 2 (CCL2) recruiting macrophages into the tumor." (PMID 32445554, 2020). "In regard to ESCC, early studies had shown the correlation of increased CCL2 expression with macrophage infiltration and tumor invasion." (PMID 32103760, 2020). "In contrast, CCL2 staining of ICs was negatively correlated with tumor stage, lymph node stage, and molecular subtype and positively correlated with OS, DSS, RFS, and CK5 staining." (PMID 32429318, 2020). "CCL2 protein expression was analyzed in tumor cells (TCs; N = 168) and in immune cells (ICs; N = 168)." (PMID 32429318, 2020). "Overexpression of IL-17D in edited tumor cells induced tumor rejection by stimulating CCL2 production from tumor endothelial cells, leading to an increase in the recruitment of NK cells." (PMID 33322371, 2020). "COX-2 induction is associated with an increased production of PGE2; therefore, COX-2 blockade was shown to suppress tumor by reducing the MDSC-attracting chemokine CCL2 and the number of G-MDSCs in the tumor microenvironment." (PMID 32443699, 2020). "Monocytes are recruited from the circulation and differentiate into macrophages within the TME where stromal and tumor cells provide chemokines and growth factors mainly CCL2, CSF1, CCL18, CCL20, CXCL12, and VEGF-A." (PMID 31256327, 2020). "(b) Quantification of tumor volume of primary tumor and bioluminescence signal at 4 weeks in mice treated with ctrl ab (n = 4), anti-Ccl2 ab (n = 4) or anti-Il13 ab (n = 3) or anti-Ccl2+Il13 abs (n = 4)." (PMID 31933479, 2020). "In animal experiments, CCL2 was shown to be responsible for increased tumor growth and metastasis due to the accumulation of CCR2-expressing macrophages." (PMID 32001710, 2020). "These cells are chemoattracted by circulating tumor cells (CTCs)-derived CCL2 into the metastatic organ." (PMID 32824655, 2020). "Treatment of young mice with VDC resulted in an increase of CCL2 plasma and tumor concentration and Arg1 in tumor." (PMID 32887237, 2020). "CCL2 is also an important chemokine secreted by tumor cells and endothelial cells to support infiltration of TAMs in tumors." (PMID 32983125, 2020). "TGF-β signaling in myeloid cells promotes CCL2-dependent MDSC recruitment to the tumor microenvironment, and granulocytic MDSC-derived TGF-β promotes EMT upon metastasis, which is the advanced form of malignancy." (PMID 32265903, 2020). "We verified these results at the protein level using Ccl2mCherry mice, which showed abundant CCL2 protein expression in the VI in tumor animals at 10 d.p.i., exclusively expressed in Iba1+CD206+ meningeal macrophages." (PMID 32391790, 2020).
tumor (continued). "As expected, treatment with CCL2 cytokine strongly increased tumour growth compared to NaCl control." (PMID 32908142, 2020). "Some chemokines were increased in LSCC samples, such as CCL2, CCL15, CCL16, and these chemokines were implicated in the angiogenesis or angiostasis balance and promoted tumor infiltrating hematopoietic cells in the pathophysiology of NSCLC." (PMID 33005178, 2020). "The majority of tumor-associated macrophages (TAMs) expressed proinflammatory cytokine/chemokine genes, such as IL1B, CCL2, CCL3, and CCL20." (PMID 33277616, 2020). "Chemokines including CCL2 and CCL5 are described to attract tumor-associated macrophages and monocytes during this infiltration process." (PMID 33207809, 2020). "Although both FOLFIRINOX and gemcitabine combined with nab-paclitaxel improve patient survival and disease response compared with single-agent gemcitabine, there is an immunosuppressive tumor microenvironment directed in part by the CCL2/CCR2 axis." (PMID 31297636, 2020). "One of the mechanisms by which some chemokines such as CCL2 or CXCL8 promote tumor growth and proliferation involves acting as autocrine or paracrine growth factors." (PMID 31991604, 2020). "For example, the tumor endothelium produces CCL2 stored in vesicles of actin fibers beneath the plasma membrane." (PMID 33381115, 2020). "Compelling evidence has shown that macrophages can be recruited to tumor tissues by some chemokines, such as CCL2." (PMID 34138195, 2020). "For instance, monocyte chemo-attractant protein 1 (CCL2) is involved in the recruitment of macrophages to the tumor microenvironment through activation of the CCR2 receptor." (PMID 32326073, 2020). "Chemokine (C-C motif) ligand 2 (CCL2) attracts monocytes that can later migrate to the tumor environment and differentiate into TAMs." (PMID 32668761, 2020). "The combined treatment with Ccl2 and Il13 increased macrophage infiltration at both the orthotopic primary tumor in the liver and pulmonary metastases (p<0.0001), with enrichment of M2-like Cd206+ TAMs." (PMID 31933479, 2020). "Their pre-clinical study further notes that MYC-amplified Group 3 MB allograft mouse tumours have a higher tendency to express CCL2." (PMID 32539808, 2020). "Tumor cells recruit Tregs from lymphoid organs by the expression of specific chemokines such as CCL2 or CCL21." (PMID 32582698, 2020). "Due to a fluctuating range in CCL2 values, we further subdivided the tumor type to cervical SCC and AC." (PMID 32064233, 2020). "This pattern was distinct from the reduced expressions of Ccl2 and Cxcl1 in tumor tissues compared with primary cells." (PMID 32244522, 2020). "Since miR-155-deficient NK cells exhibit impaired chemotaxis to CCL2 ex vivo, we explored the possibility that they would also fail to traffic to a CCL2-rich tumor site." (PMID 32040476, 2020). "For example, CCL2 is a member of the C-C type chemokine family secreted by tumor cells or TAMs to promote TAMs recruitment." (PMID 33363016, 2020). "CCL2 is often overproduced in the tumor microenvironment, including that of breast, and attracts T cells, monocytes, and NK cells." (PMID 32040476, 2020). "From IHC results, CCL2 indeed showed high expression in tumor tissues, especially liver metastatic tissues." (PMID 32489462, 2020). "Monocytes enroll in the tumor tissue as a result of chemokine CCL2 and macrophage colony-stimulating factor." (PMID 32260363, 2020). "M-MDSCs and inflammatory monocytes migrate to the tumor site via the CCL2/CCR2 pathways and differentiated into TAMs in response to various factors secreted by tumor cells." (PMID 33384962, 2020).
tumor (continued). "Preferential migration of T cells to tumor tissues can be induced by tumor-associated chemoattractants such as CXCL 9, 10, 11, and CCL2." (PMID 32083009, 2020). "When these monocytes then become recruited to the tumor tissues by CCL2, they facilitate tumorigenesis by promoting immune suppression, extracellular matrix remodeling, angiogenesis, and tumor cell intravasation into the vasculature." (PMID 32824016, 2020). "Tumor cell-produced CCL2 induces monocyte infiltration into tumor tissue and differentiates into TAM in the TME." (PMID 32707869, 2020). "It was found that under such interactive settings, CCL2 has contributed to elevated tumor cell migration, generation of CSCs and angiogenesis." (PMID 32582148, 2020). "The process of migration occurs through chemotaxis and is conditioned by tumor-released ligands, such as chemokine (C-C motif) ligand 2 (CCL2), CCL5 and colony stimulating factor 1 (CSF-1)." (PMID 32488850, 2020). "Within the tumor microenvironment, we observed that elevated CCL2 expression enhanced recruitment of macrophages during early tumor growth, followed temporally by significant increases in CAF formation and collagen deposition." (PMID 32731354, 2020). "CCL2 is positively correlated with MDSCs in tumor tissues, suggesting that it promotes MDSC migration to tumor tissues." (PMID 32000802, 2020). "Endothelial progenitor cells expressing CCR2 can be recruited from the circulation in response to tumor expression of CCL2, contributing to tumor angiogenesis." (PMID 31690961, 2020). "Exosomes from tumor cells package assorted proteins and chemokines with immunomodulatory capability, including CSF-1, CCL2, and TGF-β, to promote M2-like characterization of TAMs." (PMID 33505964, 2020). "A reduced macrophage recruitment was mediated by a reduced chemotaxis factor CCL2 production of tumor cells resulting from a nuclear factor- κB (NF-κB) pathway blockade mediated by CUL1 inhibition." (PMID 33233664, 2020). "The expression levels of CCL2 were higher in tumor tissues in the RKO/ETV5+Bev group compared to those in the RKO/Vector+Bev group in vivo." (PMID 33099574, 2020). "Tumor-derived CCL2 is a monocyte-chemotactic protein and its high level correlates with high numbers of TAMs in tumor tissue and a poor prognosis." (PMID 32595638, 2020). "Both cell lines secreted Gm-csf, Tnf-α, Ccl-2, Ifn-γ, and IL-1α while Timp1 was uniquely secreted by the PyMT+ tumor line." (PMID 31941005, 2020). "Further, the binding of S100A7 and RAGE leads to the recruitment of TAMs, which then promote further tumour growth, angiogenesis, and metastasis by expressing chemokine (C-C motif) ligand 2 (CCL2), cyclooxygenase-2 (COX2), and VEGF." (PMID 32722137, 2020). "We found that in the tumor and the tumor microenvironment, CCL2 and CXCL10 localized in Nestin+, Iba-1+, CD16+ and CD163+ cells." (PMID 32943658, 2020). "PARP1 inhibition in CCL2 expressing cancer cells can alter not only the cancer cells themselves but also the surrounding cells in tumor stroma." (PMID 32455851, 2020). "CCL2 (also called monocyte chemotactic protein-1 [MCP-1]) is a member of the MCP chemokine family that is produced by tumor cells and stromal cells such as myeloid cells, ECs and fibroblasts and acts as a chemoattractant for T cells, NK cells and monocytes." (PMID 32850861, 2020). "On the contrary, tumor cell-derived paracrine signals contribute to M2-like macrophages, including IL-10, CSF-1, different chemokines (CCL2, CCL18, CCL17, and CXCL4), and various extracellular matrix components." (PMID 32653013, 2020). "Once recruited to the tumor microenvironment in a CCL2-dependent manner, macrophages differentiate into tumor-associated macrophages (TAMs)." (PMID 32824655, 2020). "Conversely, the mRNA expression of S100A14, IL1A, CCL2, CXCL3 and CXCL5 in tumor tissues derived from S100A14-deficient mice was significantly reduced compared with those from their WT counterparts." (PMID 32483412, 2020).